IL6 (interleukin 6)
Diseases named in the same sentence as IL6 in open-access papers (continued):
Sharing a sentence is not in itself a finding about the gene and the disease.
Stroke (continued). "The sexual dimorphism in the Vtn effect on neurogenesis is caused by a different level in the expression of IL-6 at D1 after stroke, and its reduction to the normal level lasts for 2–3 days." (PMID 38107409, 2023). "In canine models of stroke, elevated IL-6 in CSF has been shown to be associated with a poorer prognosis, and, more recently, IL-6 has been shown to be elevated in the CSF and plasma of dogs with naturally occurring stroke." (PMID 37266378, 2023). "In concordance with these previous reports, our study revealed that IL‐6 concentrations were positively associated with stroke recurrence and functional disability as well." (PMID 37287421, 2023). "Per stand deviation (4.26 pg/mL) increase in the concentration of IL‐6 was associated with an increased risk of stroke recurrence (adjusted odds ratio [aOR], 1.19; 95% CI, 1.09–1.29) and disability (aOR, 1.22; 95% CI, 1.15–1.30) within 90 days." (PMID 37287421, 2023). "Enhanced levels of blood IL-6 are associated with an increased risk of stroke and contribute to racial differences in stroke through the influence of inflammatory risk factors." (PMID 36769472, 2023). "Blood inflammatory markers, such as high-sensitivity c-reactive protein (hsCRP) and interleukin-6 (IL-6) are independently associated with first stroke and recurrent vascular events after ischemic stroke/TIA." (PMID 37626883, 2023). "Numerous clinical studies have examined the association between IL-6 and cardiovascular health, particularly in stroke, with many lines of evidence suggesting it serves as a strong predictor for stroke, atherosclerosis and adverse cardiovascular events." (PMID 37685924, 2023). "In 4,893 patients with AF in the RE-LY trial, raised IL-6 was independently associated with a two-fold risk of stroke or systemic embolism (Q4 vs. Q1, HR 2.03, 95% CI 1.27–3.26), adjusted for vascular risk factors." (PMID 41541100, 2023). "In the multivariable analysis including dysphagia, stroke severity and reduced consciousness at 24 h as covariables, levels of IL-6 were significantly associated with the development of LRTIs." (PMID 36430226, 2022). "It has been shown recently that pretreatment with a Jak2 inhibitor (AG490) in a rodent stroke model alleviated brain endothelial cell barrier disruption and decreased the reduction of tight junction ZO-1 protein caused by IL-6." (PMID 36145501, 2022). "IL-6 is the most well-known biochemical marker of stroke and is associated with a poor 3-month and 12-month prognosis." (PMID 35629013, 2022). "Studies in other populations, such as patients with prior stroke and polyvascular disease, show an increased risk of recurrent stroke in patients with elevated IL-6 levels." (PMID 36319844, 2022). "Elevated serum IL-6 levels are implicated in a higher risk of incident stroke and mediate the racial disparity in stroke via inflammatory effects of risk factors." (PMID 35173738, 2022). "IL-6 is also an independent predictor of the composite endpoint of stroke or death in patients with AF and is associated with worse outcomes after ischemic stroke." (PMID 36211709, 2022). "When considering the subgroup of LRTIs, in patients who presented early (≤12 h after stroke, n = 139), IL-6 was independently associated with LRTIs (OR: 1.073, 95% CI: 1.002–1.148)." (PMID 36430226, 2022). "In the patients with ischemic stroke or TIA, we found independent associations of IL-6 or YKL-40 with recurrent stroke, composite vascular events and poor functional outcome, which were more apparent than that of hsCRP and Lp-PLA2 mass and activity." (PMID 35761288, 2022). "For instance, poor functional outcomes (measured using the European stroke scale and BI) were associated with a high concentration of IL-6 after 3 months of hospital admission in samples taken within 36 h of the stroke event." (PMID 36699006, 2022).
Stroke (continued). "Many authors indicate that the rise in the concentration of IL-6 in the blood serum on the first day after a stroke is associated with the deterioration of the functional status of patients and a greater extent of the ischemic focus." (PMID 36142524, 2022). "In human stroke victims, gut dysbiosis was shown to be associated with serum inflammatory markers, interleukin-6, C-reactive protein, and white blood cell counts." (PMID 35052672, 2022). "And in a study of 130 patients with CSVD, IL-1α and IL-6 was found a significant association with recurrent stroke and other vascular events, and there was a correlation between IL-6 and deep WMH." (PMID 36119691, 2022). "Elevated levels of CRP and interleukin-6 were associated with an increased CMB burden in the stroke cohorts and more pronounced in APOE-ε4 carriers." (PMID 36119691, 2022). "On the other hand, we analyzed the levels of IL-6, an inflammatory biomarker in stroke associated with poor prognosis." (PMID 34300300, 2021). "Higher levels of proinflammatory cytokines, like IL-6, are also associated with worse neurological outcomes in patients post-stroke." (PMID 34393969, 2021). "We found that exhaled decanal tracks CRP and IL-6 levels post-stroke and correlates with several metabolic pathways associated with a post-stroke inflammatory response." (PMID 34753981, 2021). "IL-6 measurement improved the prediction of incident heart failure, stroke, and all-cause mortality, particularly among statin users." (PMID 32748207, 2021). "Several studies showed that an elevated level of IL-6 was associated with brain infarction volume, stroke severity, and prognosis of IS." (PMID 33927687, 2021). "In multivariate logistic model, after correcting conventional risk factors and TOAST subtype, both CRP and IL‐6 level were independent predictors for mortality, stroke severity, and mRS‐defined outcome." (PMID 33314753, 2021). "Two recent two-sample MR studies using more SNPs further confirmed the causal effect of IL6 signaling on coronary heart disease, as well as the causal effect of IL6 signaling on atrial fibrillation, stroke and AA." (PMID 34168680, 2021). "Taken together, miR-9, miR-124, miR-134, miR-152-3p, and miR-223 are associated with the severity of stroke; miR-134 and miR-223 with poor prognosis; miR-9, miR-124, and miR-134 with the infarct volume and the level of IL-6." (PMID 34070696, 2021). "Secondly, we analyzed interleukin-6 (IL-6), a pro-inflammatory molecule implicated in the early stages of stroke which has also been shown to be involved in different pathways that increase the severity of damage and patient outcome." (PMID 34300300, 2021). "In a different study, IL-6 was an independent predictor of SAI in a cohort of 82 stroke patients and was also associated with mortality." (PMID 34092245, 2021). "The best biomarkers identified in the present study are known key players in pathophysiological pathways implicated in stroke, such as angiogenesis (endostatin) and inflammatory response (IL-6 and TNF-R1)." (PMID 33578805, 2021). "A recent review highlighted that changes in molecular biomarkers such as C-reactive protein (CRP), interleukin 6 (IL-6) and IL-10 in blood, urine, and other body fluids are associated with post-stroke cognitive decline." (PMID 33671531, 2021). "In conclusion, increased IL-6 and reduced IL-10 concentrations are present in the early stroke period and are associated with a degree of neurological deficit and stroke outcome." (PMID 33922467, 2021). "Elevated IL-6 and fibrinogen levels in early subacute stroke were associated with worse outcome up to 6-months after stroke." (PMID 34512526, 2021). "One specific protein relationship studied was interleukin 6 (IL-6) as it has been shown to be related to stroke risk factors, infarct volume, and clinical outcomes." (PMID 33971895, 2021).
Stroke (continued). "This study demonstrated that PolyVD together with the elevated IL-6 levels increased the risk of stroke recurrence, MACEs, all-cause mortality, and poor functional outcomes in patients with AIS or TIA at 1-year follow-up." (PMID 33927687, 2021). "Previous studies using the two-sample MR method have confirmed the causal effect of IL6 signaling on a range of cardiovascular phenotypes including stroke, coronary heart disease, and aortic aneurysm (AA)." (PMID 34168680, 2021). "Another clinical ischaemic stroke study demonstrated that higher IL-6 levels 1 day post-stroke were associated with poor mRS outcomes and shorter survival times 3 months post-stroke." (PMID 34884906, 2021). "We found that higher systemic and intracranial levels of IL-6 were associated with higher NIHSS admission scores thereby further confirming previous studies’ results of IL-6’s role in the acute phase of stroke." (PMID 35126360, 2021). "In this study, we aimed to explore an association between ex vivo cytokine synthesis, circulating IL-6 as a marker of systemic inflammation and stroke prognosis." (PMID 31906994, 2020). "Within the stroke patient population, we found that increased age was significantly positively associated with higher levels of IL-6 (p=0.015) and IL-8 (p<0.0001) in serum 24 hours after stroke." (PMID 31927534, 2020). "Following multivariable adjustment, only IL-6 and tumor necrosis factor-alpha remained significant predictors of stroke risk." (PMID 32154260, 2020). "Blocking the isolation-induced loss of brain IL-6 leads to improved outcomes after stroke, suggesting that IL-6 signaling differs more in the brain than in the peripheral tissues." (PMID 32325813, 2020). "Over-nutrition as a risk factor for stroke, enhances formation of inflammatory mediators such as c-reactive protein, tumour necrosis factors, intracellular adhesion molecule and interleukin-6." (PMID 33598073, 2020). "Serum vitamin D levels are inversely associated with interleukin (IL)-6 and high-sensitivity C-reactive protein (hsCRP) levels in stroke individuals, consistent with a potential anti-inflammatory role of vitamin D after stroke." (PMID 32316584, 2020). "Our studies demonstrated that age was associated with higher serum levels of IL-6, a pro-inflammatory cytokine that accelerates neutrophil release and migration, in both human stroke patients and our experimental mouse model." (PMID 31927534, 2020). "Poor sleep quality is related to impaired glucose tolerance and insulin sensitivity, and increased interleukin 6 level, and plasma concentration, which increases the risk of stroke." (PMID 32457400, 2020). "In order to identify the MC-derived products that influence stroke pathology, BMCMCs derived from two candidate factor-deficient mice (IL-6 and CCL7) were injected into the meninges of MC-deficient mice." (PMID 31001088, 2019). "For example, in a meta-analysis of 4112 stroke patients from 20 studies, IL6 was associated with poor outcome, defined as MRS score of >2 or BI score of <85, as well as post-stroke infection." (PMID 30934019, 2019). "Mediation analysis showed that the risk of CE-stroke was largely driven by the association between IL6 signaling and the risk of AF." (PMID 31552141, 2019). "In patients with atrial fibrillation, increased IL-6 seems to be related to higher risk for both stroke and major bleeding, as well as to thromboembolic events and vascular death." (PMID 31269910, 2019). "Several lines of evidence demonstrate that stroke- and inflammation-induced neurotoxicity is associated with elevated IL-6." (PMID 30915140, 2019). "In line with the present findings in AF, we found a potential causal role for IL6 signaling in CE-stroke." (PMID 31552141, 2019). "Higher IL-6 levels after stroke have been associated with poor outcome, but the additional value over clinical data was moderate." (PMID 31269910, 2019).
Stroke (continued). "SAP, lower mHLA-DR-expression and higher IL-6 levels on day one are associated with poor outcome and shorter survival time at 3 months after stroke onset." (PMID 31269910, 2019). "A recent report recommended that IL-6 induced by IL-1 was associated with worse prognosis in stroke patients, and that clinical outcome would be improved after the inflammatory factor was reduced by IL-1 receptor antagonist." (PMID 31164999, 2019). "Stroke severity at admission as measured by National Institute of Health Stroke Scale (NIHSS) score was associated with IL-6." (PMID 30828313, 2019). "Multi-trait analyses showed a causal role for IL6 signaling in different disorders including causal associations with AF and stroke, and also identified causal associations with atopic disorders." (PMID 31552141, 2019). "Multivariable Cox regression adjusted for clustering by centers revealed SAP and higher IL6-levels on day 1 as being associated with shorter survival time in the 3 months after stroke onset." (PMID 31269910, 2019). "Previous studies showed that the elevated levels of serum and cerebrospinal fluid IL6 were associated with poor stroke prognosis." (PMID 31183363, 2019). "Serum vitamin D was inversely associated with the levels of interleukin-6 and C reactive protein, suggesting a potential anti-inflammatory role for vitamin D underlying in stroke." (PMID 31315602, 2019). "Taking together, post-stroke delirium was associated with both immunodepression and systemic inflammation reflected by elevated circulating IL-6." (PMID 29669581, 2018). "TNF-α and IL-6 released by astrocytes are among the main pro-inflammatory cytokines implicated in the BBB dysfunction induced by stroke." (PMID 29452577, 2018). "Higher concentrations of IL-6 and IL-18 were also independently associated with depressive disorders in patients after stroke, and depression severity correlated positively with serum concentrations of IL-6 and IL-18 in hemodialyzed patients." (PMID 30092066, 2018). "The plasma hs-CRP and serum IL-6 are important markers of inflammation and associated with the development of stroke." (PMID 30514242, 2018). "Interleukin 6 is still associated with worsening in muscle activity, assessing the detrimental role of inflammatory cytokines in stroke-dependent muscle damage." (PMID 28373915, 2017). "Both clinical and animal studies show that a multitude of cytokines such as IL-6 and IL-10 are activated after stroke, induce stroke-associated immunodepression, and greatly increase the risk of infection." (PMID 27409177, 2016). "Among these inflammatory biomarkers, IL-6 is well known to play an important role in acute inflammatory response triggered by cerebral ischemia, and an elevated blood IL-6 concentration is associated with poor outcome after stroke." (PMID 27146847, 2016). "Previously, research had shown that proinflammatory cytokine changes of IL-1 and IL-6 associated with stroke were related to PSF." (PMID 26166952, 2015). "IL-1β and TNF-α have been associated with exacerbation of injury in stroke while IL-6 has been found to be neuroprotective." (PMID 26074992, 2015). "Initially, a small study reported an association between IL-6 and a composite outcome of stroke and death." (PMID 25215263, 2014). "In stroke patients, IL-6 has been linked to early neurological deterioration (END), greater infarct volumes and poorer long-term outcome." (PMID 25086655, 2014). "We found that circulating IL-6 and hFABP levels showed an independent association with stroke prognosis after adjusting for clinical covariates." (PMID 23497639, 2013). "Our finding of the strong association between IL-6 and poor stroke outcome is consistent with those of several studies using multiple blood markers in prospective stroke cohorts." (PMID 23497639, 2013). "Mice deficient in IL-6 showed similar stroke lesion volume and neurological function as control mice in an acute ischemic injury model." (PMID 23431245, 2013).
Stroke (continued). "An elevated IL-6 level is associated with an increased infarct volume and severity of stroke outcome." (PMID 23690990, 2013). "High levels of CRP, which is an acute-phase protein released by the liver in response to IL-6, are linked to worse outcome following stroke, and acute prestroke administration of human CRP is deleterious in experimental models." (PMID 22474516, 2012). "Higher levels of IL-6 and acute phase proteins are associated with poorer functional outcome after stroke, and one potential mechanism for the association with poor outcome is an increase in brain temperature." (PMID 23326261, 2012). "Marker of tissue injury MMP-9 and pro-inflammatory cytokine IL-6 were associated with acute lesion volume and with admission National Institutes of Health Stroke Scale (NIHSS)." (PMID 21871109, 2011). "Higher stroke severity, larger hematoma volume, larger edema volume, intraventricular extension, mass effect, and higher baseline IL-6 and TNF-α were associated with poor clinical outcome." (PMID 20936104, 2010). "We assessed the additional predictive utility of IL-6 with risk stratification tables applying cut points for predicted outcome that are relevant for stroke practice for the treatments that are currently available." (PMID 19901973, 2009). "A systematic search of the literature revealed that previous studies that had looked at the potential association between interleukin-6 levels and outcome after stroke had found similar results." (PMID 19901973, 2009). "Elevated circulating IL-6 also enhances risk of stroke and dementia in older individuals and has been shown to predict future cognitive decline." (PMID 19436757, 2009). "We have demonstrated that blood markers of the acute inflammatory response, in particular IL-6, are associated with death and poor outcome after stroke." (PMID 19901973, 2009). "There is some evidence that high levels in the blood of inflammatory markers (for example, interleukin-6 and C-reactive protein) are associated with poor outcomes after stroke—inflammation is the body's response to infection and to damage." (PMID 19901973, 2009). "We performed a systematic review of the literature and meta-analysis of the association between interleukin-6 and poor outcome after stroke to place our study in the context of previous research." (PMID 19901973, 2009). "Similarly, IL‐6 levels predict incident stroke, with each SD rise linked to a 19% higher stroke risk, as confirmed in meta‐analyses of multiethnic diabetic cohorts." (PMID 41567175, 2026). "Clinical evidence shows that blood and cerebrospinal levels of IL6 are significantly elevated in patients following stroke; the JAK/STAT3 pathway is highly implicated in post-stroke inflammation by inducing the transcription of inflammatory mediators like cytokines and chemokines." (PMID 40362325, 2025). "Elevated IL-6 levels after a stroke may be associated with mortality, adverse short- and long-term outcomes, and functional status, assessed using the modified Rankin Scale (mRS) at 3 months and 1 year." (PMID 40305179, 2025). "Genetic predispositions may influence stroke risk, as polymorphisms in inflammatory markers (e.g., C-reactive protein, interleukin-6) have been associated with a threefold increase in postoperative stroke." (PMID 40278202, 2025). "After IL-6 signaling inhibition, the potential for an increased risk or exacerbation of stroke cannot be conclusively ruled out because the intricate role of IL-6 in the context of stroke is multifaceted." (PMID 40526615, 2025). "IL-6 plays a role in the pathogenesis of stroke, especially the atherosclerotic stroke of large arteries, and is associated with disease progression and functional outcomes within 3 months of the stroke." (PMID 40305179, 2025).